INS (insulin)
Diseases named in the same sentence as INS in open-access papers (continued):
Sharing a sentence is not in itself a finding about the gene and the disease.
Cognitive impairment (continued). "Therapeutic interventions aimed at improving CNS insulin sensitivity are being increasingly noted for their ability to modulate both cognitive impairment and neuroinflammation." (PMID 40806709, 2025). "This cognitive impairment arises from complex interactions among insulin resistance, chronic inflammatory responses, vascular injury and microangiopathy and oxidative stress." (PMID 40831951, 2025). "In trials of people with other cognitive issues, including mild cognitive impairment or AD, the effects of intranasal insulin on various outcome measures have been mixed." (PMID 40253245, 2025). "Together, we demonstrated that ApoE4 exacerbated cerebral AD‐like pathologies and cognitive impairments in T2DM mice by modulating insulin signaling pathways." (PMID 40905109, 2025). "Recently published studies show that physical activity can reverse insulin resistance in the brain as well as cognitive impairment and pathological appetite regulation." (PMID 39876043, 2025). "Another study also reveals a significant trend towards increased risk for mild cognitive impairment (MCI) with high plasma BACE1 level and insulin resistance in type 2 DM patients." (PMID 41446639, 2025). "Intranasal administration of insulin has been shown to restore insulin signaling pathways, reduce amyloid and tau burden, improve mitochondrial function, and reverse cognitive impairment." (PMID 41294899, 2025). "Dapagliflozin has therapeutic potential in alleviating cognitive deficits and neurodegeneration primarily due to its insulin-sensitizing and antioxidant properties, along with its capacity to enhance mitochondrial function." (PMID 40397120, 2025). "STZ-icv treatment results in an insulin-resistant brain state, cognitive deficits, and reduced hippocampal adult neurogenesis (AN)." (PMID 40646278, 2025). "A substantial body of experimental and clinical evidence supports the effectiveness of intranasal insulin in treating chronic neurodegenerative diseases such as Alzheimer's disease, Parkinson's disease, mild cognitive impairment, and neuropathy." (PMID 41312480, 2025). "Studies have shown that the insulin-sensitising effect of exercise is also manifested in the brain, which gives exercise the power to prevent or decrease these cognitive deficits." (PMID 40274715, 2025). "Another mechanism through which irisin improves cognitive impairment involves its role in insulin signalling, especially in the context of insulin resistance." (PMID 40660735, 2025). "The treatment enhanced glucose uptake and insulin sensitivity in vitro, reducing cognitive deficits, Aβ burden, and neuroinflammation in vivo." (PMID 39859201, 2025). "The present study found that hesperetin, a flavanone derived from citrus peel, enhanced metformin’s efficacy in reducing blood sugar levels, improving insulin sensitivity, and ameliorating cognitive impairment in diabetic rats." (PMID 40076550, 2025). "The use of insulin in the treatment of mild cognitive impairment and AD dementia shows considerable potential." (PMID 40153574, 2025). "It resembles many aspects of AD, known with cognitive impairments, amyloid and tau pathology, neuroinflammation, oxidative stress, impaired insulin signaling, and neurovascular changes." (PMID 40720390, 2025). "Intranasal insulin delivery, bypassing peripheral insulin resistance, has shown cognitive benefits in patients with mild cognitive impairment (MCI) and early-stage AD." (PMID 40806709, 2025). "We investigated OGTT and other glycaemia and insulin resistance markers, and cognitive and neuroimaging changes in the Finnish Geriatric Intervention Study to Prevent Cognitive Impairment and Disability (FINGER)." (PMID 40478656, 2025). "Experimental studies have shown that high‐fat diets, which induce metabolic disturbances such as insulin response, can also lead to brain insulin resistance, mitochondrial dysfunction, and cognitive impairment in animal models." (PMID 40823947, 2025).
Cognitive impairment (continued). "Based on this, we link CRS and subsequent insulin resistance to neuronal oxidative stress, which negatively impacts Aβ and tau, contributing to cognitive impairment and AD pathophysiology." (PMID 40397120, 2025). "Insulin secretion is primarily regulated by the PI3K-AKT-GSK/3 signaling pathway, where GSK-3β serves as a key protein associated with both cognitive impairment and glycemic regulation." (PMID 40417692, 2025). "The treatment normalized hippocampal FNDC5/irisin expression, which was associated with a reduction in Aβ and P-tau proteins, improved BDNF and insulin signaling, and alleviated cognitive impairments." (PMID 40018518, 2025). "The T2DM patients carrying the ApoE ε4 allele exhibit heightened activation of platelet glycogen synthase kinase‐3β (GSK‐3β), a key downstream kinase in the insulin signaling pathway, along with more severe cognitive deficits." (PMID 40905109, 2025). "Beyond the mild cognitive impairment/AD spectrum, intranasal insulin has shown benefits for cognition as well." (PMID 40253245, 2025). "Increased levels of fasting plasma glucose, 2 h postprandial glucose, HbA1c and fasting plasma insulin are important determinants in the development of cognitive impairment, especially in carriers of the APOE4 gene." (PMID 40430451, 2025). "As anticipated, dapagliflozin improved insulin resistance and glucose metabolism and reduced cognitive impairment in female mice fed with a HFD." (PMID 39972998, 2025). "Research on intranasal insulin in Alzheimer’s and mild cognitive impairment shows that it is a safe and effective way to target insulin signaling in neurodegeneration." (PMID 39458902, 2024). "This study aimed to establish a cognitive impairment model through intracerebroventricular injection of lipopolysaccharide (LPS) and explore the impact of intracerebroventricular insulin injection on cognitive function in mice." (PMID 39073013, 2024). "Our findings underscore the therapeutic potential of insulin in alleviating LPS‐induced cognitive impairment and ferroptosis by modulating glucose metabolism." (PMID 39073013, 2024). "This review examines the critical role and efficacy of intranasally administered insulin, elucidating its neuroprotective effects in individuals with both DM and pre-existing cognitive impairment." (PMID 38441832, 2024). "It has been demonstrated that intranasal administering of insulin can improve memory function in people with AD or mild cognitive impairment." (PMID 39822457, 2024). "Additional studies have suggested that exercise potentially reduces insulin resistance and cognitive impairment by improving endoplasmic reticulum stress." (PMID 38818523, 2024). "This process is crucial in modulating inflammatory responses and insulin signaling pathways, both of which are key contributors to the development of cognitive deficits in T2DM patients." (PMID 38963109, 2024). "Insulin dysregulation in the brain has garnered heightened interest in recent years due to growing evidence linking impaired insulin signaling to various neurological and cognitive disorders." (PMID 39596023, 2024). "In terms of cognitive function, the TMAO inhibitor 3,3-Dimethyl-1-butanol (DMB) can restore cognitive deficits in aging mouse models by alleviating neuroinflammation and enhancing insulin resistance." (PMID 39430973, 2024). "The MWM and Y maze assessments were used to evaluate the protective efficacy of insulin treatment against hippocampus‐dependent cognitive impairment induced by LPS." (PMID 39073013, 2024). "A 1 μ/L increase in insulin resulted in a 6% decrease in the incidence of cognitive impairment (OR = 0.94; p-value = 0.009)." (PMID 38542318, 2024). "One study observed that individuals with AD or mild cognitive impairment (MCI) randomized to chronic INL insulin exhibited attenuated declines in FDG PET uptake over time compared to those randomized to placebo." (PMID 37611907, 2024).
Cognitive impairment (continued). "These processes include amyloidogenesis, tau hyperphosphorylation, neuroinflammation, oxidative stress, endoplasmic reticulum stress, insulin resistance, synaptic dysfunction and cognitive impairment." (PMID 39273520, 2024). "Insulin improves LPS‐induced cognitive impairment and alleviates LPS induced ferroptosis by promoting pentose phosphate pathway of glucose metabolism." (PMID 39073013, 2024). "Our findings highlight insulin's multifaceted neuroprotective effects in the context of neuroinflammation‐induced cognitive impairment." (PMID 39073013, 2024). "Treatment with vildagliptin on HFD rat significantly elevates neuronal GLP-1 level, increased brain insulin signaling and attenuated cognitive impairment." (PMID 39897964, 2024). "Pilot clinical trials of intranasal insulin administration in individuals with mild cognitive impairment or AD indicate that acute and prolonged intranasal insulin administration can enhance memory performance." (PMID 38167548, 2024). "Blood plasma biomarkers such as insulin, apolipoprotein A, HDL, insulin-like growth factor, and vitamin D were associated with cognitive impairment." (PMID 38542318, 2024). "Firstly, diets rich in sugar and high-glycemic-index (GI) foods can exacerbate fluctuations in blood glucose and insulin levels, worsening the occurrence of cognitive impairment." (PMID 39200168, 2024). "The administration of intranasal insulin, as demonstrated in clinical studies, has proven effective in enhancing cognitive function across various cognitive disorders." (PMID 39073013, 2024). "Intranasal insulin in preclinical studies improved cognitive deficits via enhancement of insulin signaling, reduction of Aβ levels, and the alleviation of brain inflammation." (PMID 38313929, 2024). "The model of cognitive impairment was induced via intracerebroventricular injection of LPS, followed by intracerebroventricular administration of insulin to evaluate its effects." (PMID 39073013, 2024). "Research on the APOE-IR relationship has largely focused on insulin and cardiovascular disease mechanisms in APOE knockout mice, as well as the effect of APOE gene variations on brain insulin metabolism in human cognitive impairment." (PMID 38956564, 2024). "In the past, researchers have demonstrated that giving mice insulin through their noses can enhance their defective spatial memory as well as their cognitive impairment and learning." (PMID 38987609, 2024). "13.6% of patients had PIR in the dimension of insulin advantage; 54.9% of patients had cognitive disorders of insulin." (PMID 39036047, 2024). "This study aims to explore the neuroprotective effects of central insulin and provide novel insights and evidence for the prevention and treatment of clinical cognitive impairments." (PMID 39073013, 2024). "Impairments in brain insulin signaling and glucose tolerance are believed to contribute to the neurodegeneration and cognitive deficits seen in AD." (PMID 39337316, 2024). "Some studies have suggested a potential link between high-fructose diets and cognitive impairment, indicating that long-term fructose consumption can lead to insulin resistance in the brain, contributing to cognitive deficits." (PMID 38396924, 2024). "In a recent study, intranasal insulin treatment ameliorated the Aβ oligomer-induced cognitive impairment in male rats when tested with the Morris water maze." (PMID 37511207, 2023). "As such, aberrant brain insulin signaling has been posited to lie at the crossroads of metabolic and cognitive disorders." (PMID 37379265, 2023). "We detect elevated insulin in CSF prior to surgery-induced delirium, and an altered carbohydrate metabolism is involved in a brain vulnerable to cognitive disorders." (PMID 37759795, 2023). "Rosiglitazone also exhibited obvious improvement in cognitive impairment, with an increase in body weight, enhancement of insulin sensitivity, and reduction of glucose levels in the brain or plasma." (PMID 37259448, 2023).
Cognitive impairment (continued). "A study looking at intranasal insulin in mild cognitive impairment (MCI) and early AD found that the apolipoprotein (apo)E genotype affected the results such that benefits were greater in those not carrying the apoE4 allele, a known risk factor for AD." (PMID 37374288, 2023). "Aberrant brain insulin signaling has been posited to lie at the crossroads of several metabolic and cognitive disorders." (PMID 37379265, 2023). "Currently, T2DM-induced cognitive impairment is characterized by altered insulin and cerebral glucose metabolism, leading to a shorter life span." (PMID 37111190, 2023). "Several pilot studies have been performed in men and women with mild to moderate cognitive impairment in which insulin or a placebo was given." (PMID 37374288, 2023). "Intranasal insulin directly elevates brain insulin and significantly ameliorates the cognitive impairment in T2D patients, suggesting that enhancing the brain insulin is feasible in treatment of AD." (PMID 37667187, 2023). "In healthy older patients with normal cognition, higher insulin predicted greater cognitive impairment on attention and verbal memory." (PMID 36900723, 2023). "Martina’s study points to cerebrovascular changes, neuroinflammation, and brain insulin resistance as the main pathological aspects linking NAFLD to cognitive impairment." (PMID 38260009, 2023). "Not surprisingly, as soon as approaches to restore and enhance insulin signaling in the brain began to be developed, they immediately start to be tested for the treatment of AD, mild cognitive impairment and other neurodegenerative diseases." (PMID 36834685, 2023). "By all accounts, old FBN rats used in this study demonstrated ample evidence of age-related decrements, including whole-body insulin resistance, cognitive deficits, and diminished resting-state network coherence relative to young (4–5 months) rats." (PMID 35798912, 2022). "Being older (B = − 0.258) and under treatment with insulin (B = − 2.919) were related with greater cognitive impairment." (PMID 36104367, 2022). "In the ICV-STZ model, intraperitoneal injection of bile acid for a long period not only improves STZ-induced cognitive deficits and glucose metabolism but also increases glucose-stimulated insulin secretion and β-cell number." (PMID 35464765, 2022). "The study found that olfactory function mediated the relationship between a diabetic parameter and an executive function, indicating a pathway throughout insulin, olfactory function, and cognitive impairment." (PMID 36699964, 2022). "Published evidence shows that intranasal insulin (INI) therapy improves cognitive deficits in animals and patients, by restoring brain insulin signaling and modifying brain protein and inflammation." (PMID 35448465, 2022). "In AD, there is progressive glucose hypometabolism parallel to cognitive impairment, and insulin plays a major neuroprotective role, countering apoptosis, beta-amyloid toxicity, and oxidative stress." (PMID 35630721, 2022). "In recent years, there has been increasing interest in the role of brain insulin signaling in the development of AD pathology and the prevention of cognitive impairment with intranasal insulin administration." (PMID 36430894, 2022). "Six weeks of treatment with intranasal insulin rescued brain insulin signalling dysfunction, ameliorated cognitive impairments, inhibited JNK activation, increased neurogenesis and reduced Aβ accumulation and plaques in 4.5‐month‐old APP/PS1 mice." (PMID 35128745, 2022). "IPA treatment significantly attenuated cognitive deficits in diabetic mice; improved insulin sensitivity; enhanced mitochondrial biogenesis, and protected the ultrastructure of synapses." (PMID 35370963, 2022). "These defects in insulin action in the CNS and specially in the hippocampus and prefrontal cortex represent a possible relationship between metabolic and cognitive disorders." (PMID 35406040, 2022).
Cognitive impairment (continued). "Insulin improves cognitive impairment in Wistar rats by reducing brain oxidative stress and increasing antioxidant systems such as SOD, catalase, and GSH." (PMID 36233271, 2022). "It has been shown in T1DM-rats or AD mouse models that both acute and chronic intranasal insulin treatment reduces β-amyloid levels and repairs insulin signaling through the downregulation of tau kinases and alleviates cognitive deficits." (PMID 35052794, 2022). "Daily treatment with 40 IU insulin modulated cognition for adults with AD or mild cognitive impairment, with the apolipoprotein E-related differences in treatment response for the primary memory composite." (PMID 34108878, 2021). "The decreased responsiveness of brain cells to insulin in regions such as hippocampus and cortex can lead to the disorder of synthesis of neurotransmitters and neuronal plasticity, which leads to cognitive impairments." (PMID 33918576, 2021). "Recent clinical evidence supports intranasal insulin administration also in memory-impaired patients such as those with mild cognitive impairment (MCI), AD, Parkinson’s disease (PD), and multiple system atrophy diagnosis." (PMID 33799976, 2021). "More recent approaches intend to use nasal insulin in a different therapeutic context, which is the nose-to-brain delivery in cognitive impairment." (PMID 34201254, 2021). "In mouse models of diabetes, decreased brain insulin signaling raised the levels of tau phosphorylation and of Aβ peptide, both of which are biomarkers of cognitive impairment." (PMID 34439769, 2021). "Peripheral infection →Disruption of hippocampal insulin signaling. → Impaired synaptic plasticity and cognitive deficits." (PMID 34795562, 2021). "Using insulin sensitizer agents or intranasal insulin recovered cognitive performance in experimental models and human AD or cognitive impairment cases." (PMID 34956794, 2021). "The ratio of cognitive impairment was higher among the participants who were on treatment with insulin when compared to those on OHA." (PMID 33552796, 2021). "It is reasonable that insulin signaling dysfunction should be responsible for the cognitive deficits because the dysfunction occurs before antipsychotic administration." (PMID 34690937, 2021). "This review briefly summarized the mechanisms linking brain insulin resistance and cognitive impairment." (PMID 34108878, 2021). "A better understanding of the relationship between brain insulin resistance and cognitive impairment will help us to design future research." (PMID 34108878, 2021). "Findings have demonstrated relationships between TNF-α and cognitive impairment and dementia, incidence of cardiovascular events, insulin resistance, frailty, and mortality." (PMID 34489672, 2021). "Examination of insulin sensitivity ex vivo using post-mortem brain tissues further revealed a positive correlation of cognitive deficits in AD and insulin resistance." (PMID 34356628, 2021). "More works are urgent to explore the nature and corelates of brain insulin resistance and cognitive deficits in schizophrenia." (PMID 34108878, 2021). "Recently, it has been demonstrated that cognitive impairment and AD progression are related to a defective insulin signaling in the hippocampus and frontal cortex." (PMID 34065168, 2021). "In augmentation, the amyloid beta (Aβ) protein aberrantly interferes with the insulin signaling cascade and acts as a nexus between insulin resistance and cognitive impairment in AD13,14." (PMID 34103557, 2021). "But few investigations have been done to illuminate the precise mechanisms linking insulin resistance and cognitive deficits in schizophrenia." (PMID 34108878, 2021). "Intranasal administration of insulin (acutely and for 21 days) improves episodic memory in patients with mild cognitive impairment (MCI) or AD and modulates beta-amyloid accumulation in early AD." (PMID 34576151, 2021).